GPC3 (glypican 3)
Diseases named in the same sentence as GPC3 in open-access papers (continued):
Sharing a sentence is not in itself a finding about the gene and the disease.
breast carcinoma (continued). "Moreover, similar results were reported by two other studies demonstrating GPC3 expression in 13% and 17% of breast cancer samples." (PMID 36676710, 2022). "Therefore, an immunohistochemistry technique was used to characterise GPC3 protein expression in a wide spectrum of breast cancers." (PMID 36676710, 2022). "Even though GPC3 expression was found in less than 20% of the breast cancer subtypes examined in general, this may be relevant to the growing use of personalised therapy." (PMID 36676710, 2022). "Generally, these findings support the assumption that GPC3 may play a role as a tumour suppressor in the development of breast cancer." (PMID 36676710, 2022). "Nevertheless, the promising data on GPC3 in the context of immunotherapy indicate that further preclinical translational research on glypicans in a breast cancer setting may be worthwhile." (PMID 33742285, 2021). "In addition to that, we have found GPC3 to be a powerful predictor for breast cancer patients overall, where high levels of GPC3 lead to longer RFS." (PMID 33742285, 2021). "Moreover, breast cancer was found to upregulate glypican-1 and syndecan-4 and to downregulate glypican-3, whereas low expression of glypican-3 promotes tumor proliferation and metastasis." (PMID 31963505, 2020). "In contrast, overexpression of GPC-3 in LM3 cells, a mouse mammary tumor cell line, decreased invasiveness and spontaneous lung metastasis compared to controls, prompting the authors to suggest that GPC-3 protected against mammary cancer progression (i.e. it acted as a tumor suppressor)." (PMID 31391540, 2019). "We present in vitro and in vivo experimental evidence supporting the hypothesis that GPC3 has a protective role against human breast cancer progression." (PMID 27507057, 2016). "To analyze whether GPC3 is able to modulate the invasive and metastatic behavior of the human breast cancer cell lines, we performed in vivo assays." (PMID 27507057, 2016). "In this study, we emphasize the inhibitory role of GPC3 on breast cancer progression." (PMID 27507057, 2016). "Moreover, silencing of GPC3 deepened the MCF-7 breast cancer cells mesenchymal characteristics, decreasing the expression of the epithelial marker E-Cadherin." (PMID 27507057, 2016). "Furthermore, it has been established that GPC3 guides MCF-7 breast cancer cells to apoptosis through a mechanism that involves the anchorage of the GPC3 core protein to the cell membrane." (PMID 25140302, 2014). "Thus, GPC3 seems to be a negative regulator of breast cancer cell proliferation, since it was shown that its ectopic expression inhibited the growth rates of 8 in a panel of 10 breast cancer cell lines." (PMID 25140302, 2014). "Upregulation of glypican-3 upon syndecan-1 overexpression may contribute to the negative effects seen on proliferation and shown to be proapoptotic in both breast cancer and mesothelioma cell lines." (PMID 23144729, 2012). "However, it remains to be definitely demonstrated whether GPC3 exerts anti-oncogenic effects in breast cancer by inhibiting Hh signaling." (PMID 40422229, 2025). "In addition, GPC3 has been shown to selectively inhibit proliferation and induce apoptosis in certain breast cancer cells and mesothelioma cells by interacting with Wnt5a to trigger non-canonical Wnt/JNK signaling and concomitantly suppress canonical Wnt/β-catenin signaling." (PMID 40422229, 2025). "Therefore, considering GPC3 gene expression as a breast cancer subtype-specific biomarker may aid in assessing breast cancer prognosis." (PMID 36676710, 2022). "Interestingly, all cases of Paget’s disease, as well as 42.9% of intraductal and 16.7% of mucinous carcinomas were found to have GPC3 expression, where it was able to significantly discriminate Paget’s disease and intraductal carcinoma from other breast cancer subtypes." (PMID 36676710, 2022).
breast carcinoma (continued). "Moreover, we utilised an updated version of an established database comprising gene expression data from breast cancer patients to assess whether the GPC3 expression has an impact on the survival rate of patients with breast cancer." (PMID 36676710, 2022). "Moreover, GPC3 may have the potential to be a molecular target for the development of new therapeutics for specific subtypes of breast cancer." (PMID 36676710, 2022). "Moreover, GPC3 may potentially serve as a selective target for development of novel therapeutics for particular subtypes of breast cancer expressing GPC3." (PMID 36676710, 2022). "GPC3 might be a new therapeutic target for preventing breast cancer cell metastasis." (PMID 27507057, 2016). "Therefore, we have suggested that GPC3 acts as a metastasis suppressor in breast cancer." (PMID 27507057, 2016). "We looked for experimentally supported interactions with GPC1, GPC3, GPC4, and GPC6 as these are the glypicans we found to have the highest impact on the prognosis of breast cancer patients." (PMID 33742285, 2021). "In summary, we have found promising results in our study suggesting the prognostic power of GPC1, GPC3, GPC6 and potentially also GPC4 expression on the survival of breast cancer patients." (PMID 33742285, 2021). "And also, GPC3, another GPC member, was previously demonstrated to inhibit canonical Wnt pathway and suppress breast cancer metastasis." (PMID 27806326, 2016). "In this study we observed that the expression of GPC3 is opposite to the invasive/metastatic ability of Hs578T, MDA-MB231, ZR-75-1 and MCF-7 human breast cancer cell lines." (PMID 27507057, 2016). "Our data indicate that GPC3 is an important regulator of EMT in breast cancer, and a potential target for procedures against breast cancer metastasis." (PMID 27507057, 2016). "GPC3 induces MET through ZEB1 pathway, and controls growth, death, migration and metastatic spread of breast cancer cells." (PMID 27507057, 2016). "Conversely, glypican-3 expression is decreased in human breast cancers, and ectopic expression of GPC3 inhibits growth of breast cancer cell lines." (PMID 25168166, 2014). "As early as in 1998, Filmus J’s team found that membrane attachment but not HS chains is required for GPC3 to induce apoptosis in mesothelioma and breast cancer cells." (PMID 40422229, 2025). "A recent article demonstrated promising results where Glypican-3 (GPC3), a cell surface proteoglycan frequently overexpressed in certain types of cancer expression, significantly differentiated MPD and IDC from other breast cancer histological subtypes." (PMID 39188449, 2024). "Consequently, as GPC3 can induce mesenchymal-to-epithelial transition (MET), it can lower the invasive and metastatic ability of breast cancer cells." (PMID 39850890, 2024). "GPC3 expression was only exhibited in Paget’s disease and intraductal and mucinous carcinomas, while other breast cancer subtypes displayed no expression at all." (PMID 36676710, 2022). "Our results are also consistent with previous studies showing weak or absent GPC3 protein expression in other breast cancer subtypes." (PMID 36676710, 2022). "Such a finding has neither been determined nor reported in other studies examining the GPC3 protein expression in breast cancer subtypes." (PMID 36676710, 2022). "In the future, GPC1, GPC3, GPC4 and GPC6 might possibly serve as a basis for the medical treatment of breast cancer patients." (PMID 33742285, 2021). "While GPC3 inhibited the canonical Wnt/β-Catenin pathway in the breast cancer cells, this inhibition did not have effect on E-Cadherin expression." (PMID 27507057, 2016). "Glypicans display different activities in tumor development, while glypican-1 overexpression in tumor cells triggers mitogenic response, absence of glypican-3 expression in breast cancer cell lines inhibits mammary tumorigenesis." (PMID 23984412, 2013).
breast carcinoma (continued). "Additionally, immunoreactivity was not determined in breast cancer specimens incubated with a blocked GPC3 antibody." (PMID 36676710, 2022). "Importantly, GPC3 expression was found more often in tumours that tested positive for the expression of hormone receptors and human epidermal growth factor receptor 2 (HER2), indicating more favourable histological subtypes of breast cancer." (PMID 36676710, 2022). "Other breast cancer histological subtypes showed a lack of GPC3 protein expression." (PMID 36676710, 2022). "Glypican 3 knock down did not alter the cell surface TFPI levels in Sum102, thus demonstrating glypican 3 as an unlikely binding molecule for TFPI in these breast cancer cells." (PMID 25617766, 2015). "Besides, AXIN2, PLAG1, GPC3, DICER1 are not connected with any breast cancer genes." (PMID 31760937, 2019).
Cirrhosis (33 papers, 2011 to 2026). A chronic disorder of the liver in which liver tissue becomes scarred and is partially replaced by regenerative nodules and fibrotic tissue resulting in loss of liver function. "This study aimed to assess the diagnostic and prognostic value of serum GPC-3 in patients with HCV-related cirrhosis who achieved SVR following DAA therapy." (PMID 41511652, 2026). "In univariate analyses, both cirrhosis and GPC3 were identified as risk factors associated with HCC recurrence, whereas PSTK/GPX4 expression did not predict the prognosis of these HCC patients." (PMID 34983546, 2022). "The diagnostic accuracy of AFP, PIVKA-II and GPC-3 for the discrimination between patients with cirrhosis and those with HCC was assessed by receiver operating characteristic (ROC) curve analysis." (PMID 33142893, 2020). "In addition, combination of GPC-3 + AFP and GPC-3 + GP73 got great diagnostic value in HCC versus cirrhosis groups; the combination of GPC-3 can also improve the diagnostic accuracy of biomarkers." (PMID 36212469, 2022). "It has been suggested that serum GPC3 level in HCC patients is higher than that in cirrhosis patients." (PMID 41471145, 2025). "Immunohistochemistry and a real-time reverse transcription-polymerase chain reaction showed that the expression levels of GPC3 were much greater in small HCC than in cirrhosis and other categories of minor lesions." (PMID 37046429, 2023). "The expression of GPC3 in HCC tissue was higher than that in cirrhosis tissue and in fibrosis tissue." (PMID 35331259, 2022). "Our aim was to investigate AFP, PIVKA-II and GPC-3 diagnostic accuracy for the detection and the prediction of HCC development in patients with cirrhosis of viral etiology under surveillance." (PMID 33142893, 2020). "For HCC patients complicated with HBV infection /and cirrhosis and undergoing liver transplantation, GPC3 positive indicates a poor prognosis." (PMID 32127929, 2020). "For example, GPC3 was up-regulated slightly in cirrhosis (×2), and greatly up-regulated in both early (×7.2) and late (×10.4) tumors." (PMID 23667740, 2012). "GPC-3 alone got good diagnostic value in patients with HCC when compared with healthy control and moderate diagnostic value when compared with patients with cirrhosis." (PMID 36212469, 2022). "In the present study, we observed that serum values of AFP, PIVKA-II and GPC-3 were significantly different between patients with cirrhosis and those with HCC; however, the best accuracy for the detection of tumors was achieved by the combination of AFP + PIVKA-II." (PMID 33142893, 2020). "More importantly, GPC3 can even distinguish dysplastic nodules in cirrhosis from early HCC." (PMID 32849835, 2020). "In this large cohort of patients with HCV-related cirrhosis who achieved SVR following DAA therapy, we observed that circulating GPC-3 levels were significantly elevated in patients with HCC and correlated with tumor burden and disease stage." (PMID 41511652, 2026). "Studies have reported that the level of serum Glypican-3 (GPC3) in HCC patients is increased, which can accurately distinguish early HCC from cirrhosis, which secsitivity around 50%–72%." (PMID 39650722, 2024). "AFP, PIVKA-II and GPC-3 were measured in serum samples collected at tumor diagnosis in the 149 patients with HCC, and at the beginning of follow-up in the 200 patients with cirrhosis." (PMID 33142893, 2020). "The RFS was compared for eleven possible prognostic factors, including gender, age, etiology, presence of cirrhosis, Child-Pugh score, histological grading, CK19/GPC3 sub-typing, tumor diameter, AFP level, macroscopic and microscopic vascular invasion." (PMID 31676847, 2019). "The RFS was compared for nine putative prognostic factors, including age, gender, presence of cirrhosis, nodule numbers, macroscopic tumor thrombi, microvascular invasion, histological grading, CK19/GPC3 expression pattern, and AFP-CV." (PMID 28276470, 2017).
Cirrhosis (continued). "RFS was compared for 8 possible prognostic factors, including gender, age, presence of cirrhosis, macroscopic tumor thrombi, microvascular invasion, histological grading, CK19/GPC3 expression pattern and tumor number." (PMID 28968990, 2017). "We first report GPC-3 distributions in cirrhosis without HCC (cohort A) and with HCC (cohort B), followed by diagnostic performance (ROC) in the overall population." (PMID 41511652, 2026). "The optimal performance of GPC3 is achieved when combined with other biomarkers: HSP70 (heat shock protein 70) + GS (glutamine synthetase) + GPC3, allowing the differentiation between early-grade HCC and dysplastic nodules arising in cirrhosis." (PMID 37046471, 2023). "Compared with the those molecules, GPC3 is rarely expressed in adult and not expressed in pathological liver cells such as hepatitis, cirrhosis, and fatty liver." (PMID 32127929, 2020). "We further confirmed the HCC development by staining of glypican 3 (GPC3) present in the frozen tumor tissue but not expressed in the cirrhosis and normal liver tissues." (PMID 32296582, 2020). "Based on statistical analysis, the reciprocal interaction of MCT4 and GPC3 tended to be observed in non-treated HCCs derived from cirrhosis." (PMID 31706332, 2019). "Glypican-3 (GPC3), a member of heparan sulfate proteoglycans anchored to the cell membrane, is highly expressed in >60% of all HCCs but not in benign hepatic lesions, hepatic cirrhosis, hepatitis, or in healthy liver tissue." (PMID 36518314, 2022). "Osteopontin may be useful as a circulating marker in HCV-related HCC and although GPC3 is present in almost all HCC tissues, circulating GPC3 is not higher in patients with HCC compared to cirrhosis alone." (PMID 23527199, 2013). "Previous evidence suggests that elevated circulating GPC-3 levels may correlate with tumor presence and aggressiveness, but its diagnostic and prognostic performance in patients with HCV-related cirrhosis with or without HCC following DAA treatment has not been defined." (PMID 41511652, 2026). "Glypican-3 (GPC3) is one such HCC stem cell marker that is a specific antigenic protein typically expressed in the liver during fetal development, but not in healthy adults or fatty liver disease, cirrhosis, and hepatitis." (PMID 37841420, 2023). "In contrast, during typical cirrhosis at 14 weeks post-HCC induction, the probe could not be retained for a long time because of the absence of GPC3 expression on the cell surface." (PMID 35331259, 2022). "GPC3 expression and staining is diagnostically important for fibrolamellar HCC, which differs clinically, histologically, molecularly, and prognostically from conventional HCC and which typically occurs in young patients without cirrhosis." (PMID 27655712, 2016).
Simpson-Golabi-Behmel syndrome (33 papers, 2007 to 2026). "GPC3 has been identified as the major gene causing Simpson-Golabi-Behmel syndrome (OMIM:312870), a rare overgrowth syndrome with multiple congenital anomalies." (PMID 41261143, 2025). "Loss-of-function mutations of the glypican-3 (GPC-3) gene are the cause of the human Simpson-Golabi-Behmel syndrome an X-linked overgrowth disorder with a predisposition to GPC3-expressing cancers." (PMID 34069554, 2021). "GPC3 knockout mice showed a distinctive phenotype: Simpson-Golabi-Behmel Syndrome (SGBS), an X-linked disorder characterized by pre- and postnatal overgrowth." (PMID 33344222, 2020). "Glypican-3 (GPC3) is a heparin sulfate proteoglycan molecule first identified by Pila and associates in patients with Simpson-Golabi-Behmel Syndrome in 19961." (PMID 28852111, 2017). "GPC3 mutations in humans and mice result in Simpson-Golabi Behmel syndrome, characterized by pre- and postnatal skeletal anomalies and craniofacial malformations." (PMID 24244720, 2013). "GPC3 is mutated in Simpson-Golabi-Behmel syndrome, which is characterized by tissue overgrowth and an increased risk of embryonal malignancies." (PMID 20868507, 2010). "Mouse Gpc3 mutants are known to display marked pre- and postnatal overgrowth of many organs, phenocopying Simpson Golabi Behmel syndrome (a syndrome caused by mutations in human GPC3)." (PMID 19732411, 2009). "Mutated GPC3 in Simpson-Golabi-Behmel syndrome results in tissue overgrowth and an increased risk of embryonic malignancies in males, while female carriers may have mild manifestations." (PMID 31053802, 2019). "Humans deficient in Gpc3 suffer from the Simpson-Golabi-Behmel syndrome (SBGS)." (PMID 30228991, 2018). "In addition to HCC, GPC3 displays loss-of-function mutations in Simpson-Golabi-Behmel syndrome, and changes in GPC3 expression levels have been detected in lung squamous cell carcinomas." (PMID 23537217, 2013). "Loss-of-function mutations in GPC3 cause Simpson-Golabi Behmel syndrome (MIM 312870), an overgrowth syndrome with multiple skeletal abnormalities (large protruding jaw, widened nasal bridge, upturned nasal tip, and broad, short hands and fingers) that is associated with increased cell proliferation." (PMID 18076769, 2007). "Loss-of-function variants in GPC3 cause the Simpson-Golabi-Behmel syndrome type 1 (SGBS), at least in part, due to increase of IHH signaling." (PMID 38894719, 2024). "GPC3-deficient mice exhibited developmental overgrowth and some of the abnormalities typical of Simpson-Golabi-Behmel syndrome (SGBS), which is a rare X-linked disorder in males carrying GPC3 mutations." (PMID 30297672, 2018). "For example, human patients with Simpson-Golabi-Behmel syndrome (SGBS), caused by mutations in a glypican member, GPC3, suffer from tissue overgrowth that eventually develops into neuroblastomas." (PMID 26583080, 2015). "The Simpson-Golabi-Behmel syndrome (SGBS) is a X-linked overgrowth/malformation syndrome caused by mutations in GPC3 and GPC4." (PMID 20360844, 2010). "Research of glypicans has increased due to the discovery that mutations of the gene encoding GPC3 results in a rare, X-linked overgrowth and dysmorphic syndrome called Simpson-Golabi-Behmel Syndrome (SGBS)." (PMID 20868507, 2010). "Simpson-Golabi-Behmel syndrome (SGBS) is a rare, X-linked overgrowth disorder caused by pathogenic variants in the GPC3 gene, which encodes glypican-3." (PMID 42220602, 2026). "This Xq26.2 deletion includes the minimal critical region of Simpson-Golabi-Behmel syndrome, especially GPC3." (PMID 37221613, 2023). "Mutations in GPC3 have been linked to Wilms tumor as well as Simpson-Golabi-Behmel syndrome (SGBS)." (PMID 31956905, 2020). "Simpson Golabi Behmel syndrome (SGBS), an X-linked overgrowth disorder characterized by a broad spectrum of clinical manifestations, is due to GPC3 loss of function mutations and primarily affects males." (PMID 31428581, 2019).